IL7 (interleukin 7)
Diseases named in the same sentence as IL7 in open-access papers (continued):
Sharing a sentence is not in itself a finding about the gene and the disease.
tumor (continued). "However, many of the mice treated with ARI2h eventually experienced tumor regrowth, with those treated with ARI2hIL-15/IL-7 relapsing more quickly than those injected with ARI2hIL-15 or ARI2hIL-2." (PMID 34298748, 2021). "Recently, Ding and co-authors showed that co-administration of IL-7 with tumour-reactive CD4+ Th cells promoted their expansion, persistence and anti-tumour activity in a mouse model, thus providing a rationale for using IL-7 as an adjuvant for CD4+ Th cell-based adoptive immunotherapy." (PMID 32183246, 2020). "Antibody blockade of IL6R inhibited tumor growth and metastasis in a TNBC mouse xenograft model, while IL7 blockade could prevent the accumulation of immune cells capable of promoting tumor growth." (PMID 33007869, 2020). "Chemotherapy with cyclophosphamide and fludarabine is used for elimination of immunosuppressive cells such as Tregs, as well as for elimination of endogenous non-tumour-specific T cells that compete with therapeutic cells for interactions with APCs and activating cytokines, such as IL-7 and IL-15." (PMID 32183246, 2020). "High expression of IL-7 also showed a negative association with tumor progression in the TNM subgroup analysis." (PMID 32381120, 2020). "Here we validated that transgenic expression of IL-7 could increase the effector function as well as promote the expansion at the tumor site." (PMID 32698361, 2020). "Similarly, the activation of the IL-7/IL-7R axis was found to promote tumor cell mesenchyma switch, migration, and invasion in-vitro, thereby showing that IL-7 stimulation can promote EMT and metastasis." (PMID 32585812, 2020). "The results of IL-7 and IL-7R levels in tumor tissues showed the similar trends as that in serum." (PMID 31138762, 2019). "Interestingly, the expression of IL‐7R was induced by the treatment of cisplatin, and IL‐7 combined with cisplatin significantly decreased the expression of IL‐7R in tumour tissues." (PMID 31599032, 2019). "Interestingly, many TCMs were demonstrated to up-regulate the IL-7 level for the inhibition of tumor growth." (PMID 31138762, 2019). "Except for the association of systemic IL-7 with tumor location in the gastrointestinal tract, there were no other significant correlations between serum interleukin concentrations and clinical features of the disease." (PMID 31185636, 2019). "Together, IL‐7 enhanced the anti‐tumour efficacy of cisplatin via JAK3/STAT5 pathway in vivo." (PMID 31599032, 2019). "In vivo results also confirmed that IL-7 only in combination with DDP could remarkably induce tumor regression with reduced levels of ABCG2 in tumorous tissues." (PMID 31915416, 2019). "Therefore, in this study, we mainly aimed at determining local IL-7 concentrations in EC, GC, and CRC, and their association with tumor location, histology, and disease advancement." (PMID 31185636, 2019). "Overall, IL-7 could restore the inhibitory effect of DDP on the tumor characteristics of the DDP-resistant cell line A549/DDP." (PMID 31915416, 2019). "IL-7 is often utilized to enhance the efficacy of tumor regression." (PMID 31915416, 2019). "Decreased IL-7 concentration around the tumor might be an additional effect of the impaired IL-7/IL-7R signaling mechanism of cancer-induced immunosuppression." (PMID 31185636, 2019). "In conclusion, these results show that IL-7 primes intestinal MAIT cells for cytotoxicity, and that antigen-specific stimulation leads to release of cytotoxic granules to the same extent in colonic and tumor-associated MAIT cells." (PMID 31073372, 2019). "In addition, a xenograft model was established to confirm the anti‐tumour effect of combining IL‐7 and cisplatin in vivo." (PMID 31599032, 2019). "Tumor location was a key factor in determining both local and systemic IL-7 concentrations." (PMID 31185636, 2019). "The expression of IL-7 and its receptor IL-7R in tumor tissues was also recovered by TCM." (PMID 31138762, 2019).
tumor (continued). "More advanced cancers have lower IL-7 concentrations in the immediate environment of the tumor." (PMID 31185636, 2019). "Moreover, in A549/DDP cell transplanted model, IL‐7 combined with cisplatin significantly reduced the expression of Ki‐67 in tumour tissues compared with cisplatin treatment and enhanced cell apoptosis." (PMID 31599032, 2019). "Moreover, the expressions of IL-7 and its receptor IL-7R in tumor tissues were also determined by Western blot assay." (PMID 31138762, 2019). "In conclusion, we found that combined TCM to DDP-based chemotherapy significantly enhanced inhibition efficiency of tumor growth while reduced the chemotherapy-induced myelosuppression and IL-7 reduction, which, in turn, restored the protective function of IL-7 and hematopoietic growth factors." (PMID 31138762, 2019). "More advanced cancers have lower interleukin-7 concentrations in the immediate environment of the tumor, which may constitute a mechanism of cancer-induced immunosuppression and facilitate disease progression." (PMID 31185636, 2019). "We determined whether tumor cell migration and invasion are specific for IL-7 and analyzed IL-7R signaling and epithelial–mesenchymal transition (EMT)-related molecules." (PMID 31061414, 2019). "In addition, the heterozygote of signal transducers and activators of transcription (STAT) 5, the main component of JAK/STAT pathway of IL-7 signaling, showed a dramatic reduction in IL-7-induced mortality and tumor development." (PMID 30373315, 2018). "Moreover, IL-7 seems to have anti-tumour effects in tumours such as melanoma, prostate cancer or glioblastoma, and potential pro-tumour effects in bladder cancer by promoting cell invasion and migration." (PMID 29554938, 2018). "IL-7 boosts antitumor immunological response via several mechanisms, including promotion of tumour-redirected cytotoxic T lymphocytes, increase of tumouricidal activity in monocytes, or diminishing TGFβ production, and thus weakening tumour-induced suppression of local immune responses." (PMID 29904108, 2018). "When normal blood monocytes were incubated with tumor ascites, elevated levels of B7-H4 was observed, whereas, the serum-free medium showed no such effect, thereby suggesting that B7-H4 expression is regulated by the tumor microenvironment, specifically IL-6 and IL-7." (PMID 30274280, 2018). "Intuitively, elevated IL-7 in IBD might confer at least some degree of protection against CRC development by promoting T cell mediated anti-tumor responses." (PMID 27866242, 2017). "IL-7 is one such cytokine capable of augmenting the function of tumor-reactive CD8+ T cells." (PMID 28939858, 2017). "Moreover, IL-7 protects T cells against tumor-induced senescence and thus abrogates their proangiogenic activity." (PMID 27866242, 2017). "Circulating IL-7 also differed with respect to tumor location." (PMID 27866242, 2017). "If systemic IL-7 reflects its intestinal expression, one of possible explanations of differences in IL-7 with respect to tumor location might be related to differences in bacterial load and composition in these two locations." (PMID 27866242, 2017). "In vivo adoptive immunotherapy (AIT) experiments demonstrated anti-tumor efficacy was equally effective using IL-2, IL-21, IL-2/21, IL-7/15 and IL-7/15/21-cultured lymphocytes vs. control or cyclophosphamide alone, even at lower doses or with greater initial size of tumor prior to treatment." (PMID 28146052, 2017). "We found that intratumoral transfer of IL-7 effectors but not IL-2 effectors caused a significant regression of tumor size in Treg-replete tumor-bearing mice." (PMID 28496990, 2017). "Taking into account advocated link between IL-7 signaling and tumor aggressiveness and hence worse prognosis, more pronounced IL-7 elevation in right colon cancers might contribute to unfavorable outcomes associated with that tumor location." (PMID 27866242, 2017).
tumor (continued). "IL-7 may up-regulate tumor-directed immune responses in a number of ways, including, but not limited to, enhancement of the cellular (Th1) immune response or selective expansion of the tumor-redirected cytotoxic T lymphocytes." (PMID 27866242, 2017). "Similarly, IL-7-mediated anti-tumour activity of T-cells was significantly enhanced in the presence of sCD127." (PMID 29261677, 2017). "We next investigated whether the refractoriness of IL-7 effectors to Treg cells will be advantageous in tumor therapy." (PMID 28496990, 2017). "Thus, enhanced infiltration of CD8+ and CD4+ effector T cells in tumors and altered balance between effector T cells and regulatory T cells in favor of immunity contributed to the augmented efficacy of IL-21 and IL-7 co-expressing tumor cell vaccine." (PMID 27571893, 2016). "Additionally, evidence suggests that IL-7R or/and IL-7 play an important role in tumor development and progression." (PMID 27821177, 2016). "In addition to tumor cells, IL-7 was reported to be expressed in immune cells, fibroblasts, and other stromal cells in vivo." (PMID 27821177, 2016). "In order to investigate whether IL-7 therapy promotes tumor rejection, groups of OT-I-reconstituted Rag-/- mice received rIL-7 every 3–4 days for 18 days starting one day prior to adoptive T cell transfer." (PMID 27447484, 2016). "Perhaps different tumor models will have a different reaction to IL-7 therapy." (PMID 25955647, 2015). "Splicing of the cytokine Il7 gene has also been observed and various spliced forms of the IL-7 have been identified in granulomatous lesions of Mycobacteria tuberculosis patients and in transformed tissues and tumor cell lines." (PMID 26703587, 2015). "Whether IL-7R should be detected in tumor sample before IL-7 administration will require further research." (PMID 25955647, 2015). "Investigators aim to utilize IL-7 to enhance the efficacy of tumor regression." (PMID 25955647, 2015). "In animal models, IL-7 has been proven to prolong the survival of tumor-bearing hosts." (PMID 25955647, 2015). "A further explanation for the increased functional antitumor activity of combining OXP with IL-7 could involve suppression of the development of Treg cells, thereby retarding tumor development and growth." (PMID 24465710, 2014). "In one study, IL-7 was only detectable in higher stages of the tumor." (PMID 24551818, 2014). "Most anti-tumor activities of IL-7 were found when it was combined with other therapeutic ways." (PMID 24465710, 2014). "The anti-tumor immune activity induced by OXP was enhanced by IL-7." (PMID 24465710, 2014). "Many studies have found that IL-7 expands and maintains effective T cells in tumor-bearing mice." (PMID 24465710, 2014). "IL-7 can potentially enhance immune responses against tumor through a variety of mechanisms." (PMID 24465710, 2014). "Similarly, the local or systemic administration of IL-7 has anti-tumor effects by enhancing immune response against tumors, especially when combined with other immune treatment." (PMID 24465710, 2014). "Furthermore, the TUNEL assay showed that the combined treatment with OXP and IL-7 induced significantly increased apoptosis of tumor cells." (PMID 24465710, 2014). "IL-7 plays an oncogenic role promoting proliferation, lymphangiogenesis and metastasis in neoplasm." (PMID 23551939, 2013). "Interestingly, we found that IL-7, IL-8 and IL-10 all correlated positively with tumor RTL and T/N RTL ratio." (PMID 23383336, 2013). "The role of IL-7 production by tumor cell is still elusive, but it may be pivotal in metastasis pathogenesis." (PMID 20067635, 2010). "Tumor-bone interaction increases IL-7 production, with an increase in IL-7 serum levels." (PMID 20067635, 2010). "Thus, interactions between tumor cells and bone increased the IL-7 serum levels, as demonstrated in patients." (PMID 20067635, 2010). "IL-7 expression in tumor masses was observed in both groups." (PMID 20067635, 2010).
tumor (continued). "The resulting consequences would likely be reduced IL-7 signaling and function such as decreased expression of anti-apoptotic molecules, less proliferation, halted cell differentiation and reduced anti-viral/tumour functions." (PMID 19690616, 2009). "Tumour cells expressed low and comparable levels of IL-7 in patients and healthy controls." (PMID 18978943, 2008). "The in vitro assay of IFN-γ production may not be fully reflective of the in vivo capacity of T cells to mediate tumor regression because CD4+ T cells cultured with IL-2 plus IL-7 had only 2% IFN-γ positive cells despite equivalent in vivo anti-tumor efficacy." (PMID 15566571, 2004). "Antitumor effects have been demonstrated for fusion proteins composed of antibodies targeting different tumor-associated antigens (e.g., CEA, EDB, EDA, GD2, EGFR, FAP) and many cytokines of the common gamma chain receptor family (e.g., IL-2, IL-15, IL-15/IL15Rα, IL-21, IL-7)." (PMID 40370435, 2025). "Notably, tumor targeting was achieved and shown relevant for the treatment efficacy of bifunctional antibody-fusion proteins with all three cytokines (IL-15, IL-21 and IL-7) in immunocompetent mouse models." (PMID 40370435, 2025). "However, other reports suggested that IL-7 may also promote tumor cell proliferation and inhibit apoptosis, contributing to a pro-tumorigenic effect." (PMID 40959273, 2025). "However, as the LX strain of NDV is non-lytic and does not induce oncolysis for at least 24 h post-infection, the release of tumor antigens and/or IL-7 may be limited." (PMID 40957993, 2025). "Thus, the combination of IL-7 and tumour vaccines has great potential for use in tumour therapy." (PMID 38675377, 2024). "IL7 was found to work in synergy with αCD25 to augment antitumor effects, demonstrating that these two drugs may be used synergistically for controlling tumor burden." (PMID 38554147, 2024). "Given that the cytokine IL-7 signaling could facilitate the accumulation of tumor-associated CD8+ T cells by hindering adenosine-mediated immunosuppression, the combination of IL-7 modulator and adenosine-A2AR inhibitors have been evaluated for treatment of solid tumors." (PMID 36859386, 2023). "Infiltrated immune cells shift their phenotypes from anti-tumor, also known as pro-inflammatory phenotypes, to pro-tumor phenotypes because tumor cells increase interleukins and chemokines such as IL-2, IL-4, IL-6, IL-7, IL-10, IL-12, and CXCL12 concentrations." (PMID 37533070, 2023). "Recent studies have indicated that IL-7 could potentially re-sensitize tumours to cisplatin." (PMID 36980567, 2023). "Consequently, cryo-thermal therapy combined with IL-7 treatment could potentially improve the outcomes of tumor models with less MDSC accumulation." (PMID 37108179, 2023). "Given the fusion of the CBD to IL-7 and IL-12, local administration may provide further advantages in certain indications in a clinical setting due to the retention of the cytokines in the tumor matrix." (PMID 38019919, 2023). "In addition to CAR-T, IL-7 also has anti-tumor effects in TCR T cells." (PMID 36142322, 2022). "Culture of CAR T cells with IL-7 and IL-15 during manufacturing has been shown to enhance T cell differentiation toward a central memory (Tcm) phenotype, enhancing the persistence and anti-tumor efficacy of CAR T cells in vivo and prolonging survival in murine models of B-ALL29." (PMID 35697686, 2022). "Since MPM cells can secrete IL‐7, as shown for some other malignant cells, the higher IL‐7 levels in PE may reflect higher tumor burden and serve as a prognostic biomarker of tumor development." (PMID 36054746, 2022). "In addition, the combination of IL-7 and IL-12 could synergistically stimulate T cells in tumors, upregulate various immune systems, enhance inflammatory states, and enhance anti-tumor effects." (PMID 36142322, 2022).
tumor (continued). "Interestingly, tumor-bearing mice show a decreased level of IL-7 in the spleen, indicating that insufficient IL-7 might fails to support the survival of activated T cells, attenuating the T cell immune responses against tumors." (PMID 36389666, 2022). "Thus, IL-7 treatment seems also to have a potential tumor-promoting effect." (PMID 34445415, 2021). "Moreover, IL-7 reportedly has a strong ability to amplify initial T cells and anti-tumor ability, while its side effects are scarce and could be tolerated by the patients, providing an opportunity for IL-7 use in tumor therapy." (PMID 34778046, 2021). "Interestingly, while some studies have suggested that IL-7 might have anti-tumor effects, other studies indicate that IL-7 might also have potential pro-tumor effects." (PMID 34445415, 2021). "Hence, the inclusion of fusion receptors such as interleukin (IL)‐4–IL‐7 chimeric cytokine receptors has the propensity to shift the inhibitory signals from IL‐4 to IL‐7 signalling – leading to proliferation and memory differentiation of T cells at the tumor site." (PMID 34188916, 2021). "Therefore, we investigated whether IL7-Fc enhanced the anti-tumor responses of activated pmel-1 CD8+ T cells in combination with rhIL-2." (PMID 34440787, 2021). "Therefore, decreasing the levels of IL-7 may be beneficial to prevent tumor development and metastasis." (PMID 33574842, 2021). "Similarly, both of our results confirmed the role of IL-7 in inhibiting tumor progression." (PMID 32381120, 2020). "By contrast, others have shown that IL-7 might have a pro-tumor function." (PMID 33816214, 2020). "Additionally, TGF-β1 can inhibit the generation of B lymphoid progenitor colonies by decreasing stromal IL-7 production to limit lymphopoiesis, and it inhibits T cell and NK cell proliferation and anti-tumour effects via promoting the function and infiltration of tumour-educated B cells." (PMID 33114183, 2020). "Thus, our current approach provided cytokine IL-7 directly to the tumor site, which could possibly avoid toxicities reported with high dose systemic cytokine administration." (PMID 32698361, 2020). "However, there was significant difference in IL-7 concentration in tumor tissue." (PMID 31185636, 2019). "Upon administration, we suspect that these IL-21/IL-2-expanded TILs or TRUCKs would be best maintained by engineering them to secrete IL-7 and IL-15, which we hypothesize will further promote their persistence and memory recall responses to prevent tumor relapse in patients." (PMID 30842774, 2019). "Overall, IL-7 is expected to broaden the amplitude of the response against malignant cells that escape the immune system by mutation and immuno-editing and should help metastatic cancer patients to restore TCR repertoire diversity for improved anti-tumor immune response." (PMID 30922400, 2019). "However, in their study, tumor IL-7 expression constituted 9% of that found in normal tissue." (PMID 31185636, 2019). "Increases in PD-L1 expression can occur on SCC cells as a result of mutations in tumor cell signaling pathways or exposure of tumor cells to inflammatory cytokines IL-1, IL-6, GM-CSF, IFNγ, TNFα, and VEGF and the gamma-chain cytokines IL-2, IL-7, IL-10, IL-15, and IL-21." (PMID 31554151, 2019). "Consistent with the tumor cell migration and invasion effects by M25 treatment, these results suggest that basal expression of EMT-related molecules in PC-3 cells may be caused by self-produced IL-7." (PMID 31061414, 2019). "Notably, Il7-expressing CAFs accounted for roughly 10% of the fibroblastic tumor stroma." (PMID 29632733, 2018). "Moreover, suggested that the elevated serum IL-7 is the result of host anti-tumour immunity." (PMID 29554938, 2018). "Since Il7-expressing stromal cells in secondary lymphoid organs contribute to the regulation of immune cell function, we assessed first whether the local ablation of these cells in the tumor would affect immune cell recruitment." (PMID 29632733, 2018).